MTA1 (metastasis associated 1)
Diseases named in the same sentence as MTA1 in open-access papers (continued):
Sharing a sentence is not in itself a finding about the gene and the disease.
tumor (132 papers, 1999 to 2026). "Overexpression of MTA1 is strongly associated with more aggressive tumor behavior, advanced stages, metastasis, and an overall poor prognosis in a range of different cancers." (PMID 40351767, 2025). "While all tumor samples were undistinguishably high using the Meuten grade system, we did observe an overall trend for higher MTA1 associated with Valli grade of 3 (p = 0.017)." (PMID 40351767, 2025). "MTA1 overexpression has been observed in several human cancers, and it has been connected to tumor invasion, a higher risk of metastasis, and an advanced clinical stage." (PMID 40660330, 2025). "Overall, these results suggest the tumor- promoting role of MTA1/COX2 in canine UC and its possible but complex association with E-cad-mediated events." (PMID 40351767, 2025). "Beside transcriptional silencing of target genes MTA1 plays an important role in other mechanisms facilitating tumor metastasis and invasion, including loss of the cell adhesion molecule E-cadherin and epithelial-mesenchymal transition (EMT)." (PMID 36689059, 2023). "The increased expression of MTA1 in the HPV-associated tumor morphologies, which are known to have a better prognosis, is contradictory to the fact that MTA1 appears to be a negative prognostic marker." (PMID 36689059, 2023). "High MTA1 expression in the nucleus was associated with advanced tumor size as well as higher FIGO grading." (PMID 36689059, 2023). "Upregulation of mta1 promotes tumor progression by reducing tumor macrophages, causing residual macrophages to transition into a TAM phenotype, and blocking the activation of cytotoxic T lymphocytes (CTLs), thereby forming an immunosuppressive TME." (PMID 37217462, 2023). "Based on our observations that SMYD3 and the NuRD (MTA1/MTA2) complex are physically and functionally associated, we next investigated if MTA1 or MTA2 have the same role of SMYD3 in tumor proliferation and invasion." (PMID 36575438, 2022). "We demonstrated that SMYD3 associated with the NuRD (MTA1/2) complex to repress the expression of some tumor suppressor genes." (PMID 36575438, 2022). "We found clues that highly expressed MTA1 is associated with immune signatures in the tumor microenvironment." (PMID 35350571, 2022). "FTO mainly played a tumor-suppressive role via reducing metastasis-associated protein 1 (MTA1) expression in an m6A-dependent manner." (PMID 35945194, 2022). "Dissociation of this pro-metastatic circuit by targeting E2F1:MTA1 assembly reduced tumor-associated macrophage infiltration in the TME." (PMID 36678712, 2022). "Then, we revealed that FTO inhibited tumor metastasis and progression in vitro and in vivo by decreasing the expression of its downstream target gene, metastasis-associated protein 1 (MTA1)." (PMID 34218271, 2021). "MiR-30c directly inhibited metastasis-associated gene-1 (MTA-1) expression and functioned as a tumor suppressor via the miR-30c-MTA-1 signaling pathway." (PMID 34122542, 2021). "Mechanistically, FTO exerted a tumor suppressive role by inhibiting metastasis-associated protein 1 (MTA1) expression in an m6A-dependent manner." (PMID 34218271, 2021). "Metastasis-associated gene 1 (MTA1) is extensively identified as an oncogene, and abnormal MTA1 expression is associated with tumor growth, invasion, and metastasis in multiple cancers." (PMID 34924813, 2021). "To generally describe the MTA1-RNA association during oncogenesis, we plotted the MTA1-RBP correlation in tumor (TCGA pan-cancer), adjacent (TCGA pan-adjacent) and normal (GTEx pan-normal) tissues." (PMID 32901005, 2020). "The MTA1 expression was associated with the age, tumor (T) stage, and grade in ccRCC patients (p < 0.05)." (PMID 33059651, 2020). "In prostate cancer, metastasis-associated protein 1 (MTA1) is oncogenic with its expression correlating with tumor progression." (PMID 30781847, 2019).
tumor (continued). "The overexpression of chromatin modifier protein, MTA1 (metastasis-associated protein 1), in PCa contributes to tumor aggressiveness and metastasis." (PMID 31487842, 2019). "High expression of MTA-1 was also associated with a poor clinical outcome, tumor recurrence and a poor therapeutic response." (PMID 30563114, 2018). "In MTA1-expressing xenografts, we detected significantly higher tumor growth in PTEN-deficient LNCaP mice - compared to the PTEN-expressing DU145-xenografts." (PMID 26943043, 2016). "We found that Pten loss resulted in a marked increase in MTA1 expression leading to activation of MTA1-dependent oncogenic and tumor progression-related signaling pathways." (PMID 26943043, 2016). "MTA1 overexpression is highly associated with poor prognosis and tumor invasiveness in patients with HCC." (PMID 27323415, 2016). "One of the known epigenetic alterations in various cancers is overexpression of the master chromatin remodeler, metastasis-associated protein 1 (MTA1), which correlates with higher grade tumor, recurrence, metastasis and poor prognosis." (PMID 26943043, 2016). "Overexpression of Metastasis-associated protein 1 (MTA1) in various cancer cells promotes tumor invasion and migration and predicts cancer patients’ poor prognosis." (PMID 26698569, 2015). "Significantly positive associations were identified between MTA1 expression and tumor diameter (p = 0.04), lymph node metastasis (p < 0.01), clinical stage (p < 0.01), but negative correlation was found with smoking status (p = 0.01)." (PMID 26698569, 2015). "The metastasis-associated gene 1 (MTA1) has been identified as one critical regulator of tumor metastasis." (PMID 23718732, 2013). "HDAC activity can also be influenced by overexpression of HDAC-associated factors such as the gene of the metastasis-associated protein-1 (MTA-1), which causes changes in the mammary gland that result in tumor cells with a metastatic phenotype." (PMID 24275784, 2012). "Increasing evidence has indicated that the human metastasis-associated gene 1 (MTA1) is a key factor in tumor metastasis." (PMID 23227138, 2012). "We previously reported that overexpression of exogenous Metastasis-associated protein 1 (MTA1) protects spermatogenic tumor cells GC-2spd (ts) against heat-induced apoptosis." (PMID 22022494, 2011). "Metastasis associated antigen 1 (MTA1) is a tumor metastasis associated candidate gene, it was originally identified by differential screening of a cDNA library from highly metastatic and non-metastatic rat mammary adenocarcinoma cell lines." (PMID 21595884, 2011). "MTA1 is closely associated with various malignancies and its up-regulation always indicates tumor recurrence and metastasis." (PMID 18940013, 2008). "Included in this panel was metastasis-associated antigen-1 (MTA1), a previously known antigen which we now report to be widely over-expressed in human and mouse tumours." (PMID 18949081, 2008). "Since MTA1 is closely associated with tumor aggressiveness and metastasis in cancer, it may be considered as a possible interceptive and therapeutic target for canine invasive UC treatment." (PMID 40351767, 2025). "Elevated HSF-1 levels drive metastasis by suppressing antimetastatic gene expression and activating pro-metastatic signaling pathways, including the upregulation of metastasis-associated protein 1 (MTA-1), which interferes with oestrogen-mediated tumor suppression." (PMID 41375025, 2025). "Metastasis-associated protein 1 (MTA1) facilitates tumor progression and metastasis." (PMID 40565190, 2025). "The MTA1 protein (Metastasis Associated Protein1) regulates tumor progression and metastasis by interaction with multiples genes and protein targets that control tumor cell transformation, angiogenesis, invasion, metastasis and resistance to therapy, and is hence regarded as the ‘hub’ of cancer." (PMID 39355129, 2024).
tumor (continued). "The antioxidant cocktail effectively inhibited the expression of MTA1 and increased the susceptibility of tumour cells to apoptosis, suggesting that antioxidants may be helpful for metastasis prevention." (PMID 36701089, 2023). "In addition, we found that markers of M2-like markers for tumor-associated macrophages were significantly upregulated in macrophages in the MTA1-high samples." (PMID 35350571, 2022). "Overexpression of MTA1 has been linked to the promotion of metastasis in animal tumor models and human cohort studies by facilitating the activation of epithelial-mesenchymal transitions, expression of angiogenic factors, cancer cell proliferation, aggressive phenotypes, and invasion." (PMID 35496301, 2022). "Moreover, upregulated MTA1 in tumor cells significantly induced infiltrated macrophages into tumor-associated macrophage phenotypes and further weakened the cytotoxic effect of CD8+ T cells." (PMID 35350571, 2022). "Higher expression of MTA-1 in RAO patients may suggest an underlying difference in tumor biology to explain differences in outcomes." (PMID 32039013, 2019). "We believe that a functional interaction between MTA1 and these two downstream pathways is critical for the acquisition of an invasive phenotype by tumor cells, offering new therapeutic approaches for targeting MTA1‐positive high‐risk tumors to prevent metastases." (PMID 30027683, 2018). "Tumor invasion and metastasis are the leading cause of mortality for cancer patients and are significantly associated with the expression of particular genes, such as MTA1." (PMID 30596107, 2018). "In addition to its involvement in the invasion and metastasis, MTA1 has been implicated in proliferation, angiogenesis, and therapeutic resistance to radiation and chemotherapy, which can eventually lead to tumor recurrence." (PMID 30596107, 2018). "Furthermore, like most tumor-associated antigens, MTA1 is expressed in the brain and weakly expressed in other healthy tissues, but most drugs cannot pass the blood-brain barrier; its side effects also need further consideration." (PMID 30596107, 2018). "In addition, studies using clinical specimen and tumor model also demonstrated a significant elevation of MTA1 in highly aggressive PCa, and that loss of MTA1 diminishes PCa invasion, bone metastasis and angiogenesis." (PMID 28973968, 2017). "The authors propose that mTOR is a molecular hub linking LMP2A and MTA1-associated tumor malignancy and might be an interesting target in NPC treatment." (PMID 27231932, 2016). "MTA1 affects various biomolecules and causes carcinogenesis and tumor progression." (PMID 26878004, 2016). "MTA1 is thought to be a downstream effector of the Myc oncogene, which could explain why increased levels of MTA1 are associated with high tumor grade and invasiveness in a variety of cancers." (PMID 26075616, 2015). "Therefore, in this report, we studied the expression pattern of MTA1 in tumor samples from NPC patients, and analyzed the association between MTA1 expression and the clinicopathological characteristics of NPC." (PMID 22537306, 2012). "Overexpression of metastasis-associated protein 1 (MTA1) has been observed in many human malignancies and is significantly related to tumor invasion and metastasis, therapeutic resistance to radiation and chemotherapy, making MTA1 an ideal candidate tumor antigen." (PMID 30596107, 2018). "When the expression of genes affecting the metastasis or suppression of tumor cells was investigated, urotensin-II increased MTA-1 and ESR1 expression and decreased Kiss1 expression." (PMID 42287353, 2026). "A significant reduction in MTA1-mediated tumor growth and angiogenesis with an induction of apoptosis were observed with Gnetin C (50 mg/kg bw, i.p.)." (PMID 40077738, 2025). "The results demonstrated that MTA1 expression correlated with aggressive clinicopathological features such as high tumor-grade, muscular/vascular invasion, and metastasis." (PMID 40351767, 2025).
tumor (continued). "Immunohistochemical analyses of canine lung metastatic tissues revealed a significantly greater staining intensity (+++) for MTA1 compared to primary tumor tissues (53.2% vs. 42.9%, p < 0.05)." (PMID 40351767, 2025). "Here, we showed, for the first time, a high expression of tumor-promoting MTA1 in canine UC clinical samples and UC cell lines." (PMID 40351767, 2025). "The highest MTA1 expression was detected when the tumor was in the urethra close to the prostate (unfortunately, we had only one sample of prostatic urethra)." (PMID 40351767, 2025). "In the current study, we found significantly higher levels of MTA1 in primary tumor tissues and metastatic sites compared to normal bladder tissues." (PMID 40351767, 2025). "MTA1 contributes to tumor angiogenesis by deacetylating HIF-1α and upregulating the production of histone deacetylase-1." (PMID 40660330, 2025). "MTA1 overexpression in metastatic ovarian cancer tissues is associated with downregulation of MTA3 and E-cadherin in tumor cells." (PMID 41584603, 2025). "Superior MTA1-mediated anticancer effects of Gnetin C also included a downregulation of oncogenic/tumor-promoting ETS2, pAkt/Akt, Cyclin D1, p-mTOR/pS6K/p4EBP1 and AR signaling." (PMID 40077738, 2025). "An analysis of eight matched primary tumor-metastasis pairs showed a trend towards higher MTA1 values in metastatic lesions compared to their primary tumors (p = 0.641)." (PMID 40351767, 2025). "A highly statistically significant difference in MTA1 IHC expression between tumor sizes was found using the Pearson's chi-square test (P = 0.000)." (PMID 40660330, 2025). "To evaluate MTA1 expression as a marker for tumor aggressiveness and metastasis in UC, we compared MTA1 expression in primary tumors from dogs without metastasis with samples from dogs with metastasis." (PMID 40351767, 2025). "IGF2BP2 is highly expressed in COAD tumor tissues and, among m6A reader proteins implicated in mRNA stability, only IGF2BP2 exhibits a significant positive correlation with MTA1 expression in COAD." (PMID 39300486, 2024). "ZEB1 promotes CRC cell growth by recruiting the NuRD(MTA1) complex, and the ZEB1/NuRD(MTA1) complex transcriptionally represses glycolysis-associated tumor suppressor genes." (PMID 39193340, 2024). "The results of limited-dilution tumorigenic assays in NOD/SCID mice indicated that the overexpression of MTA1 significantly improved tumor initiation." (PMID 39154024, 2024). "The tumor growth speed of mice in MTA1 overexpression group was significantly faster and the volume and weight of tumor in this group were significantly larger and heavier with the comparison of control group." (PMID 39154024, 2024). "Our preliminary data relies on the computational methods to identify VEGF, FAK and MTA1 as targets for Terminalia elliptica derived Chebulagic acid and Chebulinic acid as probable therapeutic candidates against tumor angiogenesis and metastasis." (PMID 39355129, 2024). "Our qChIP results showed that MTA1 transcriptionally regulates tumor suppressors, including MTA3 and TRIM21." (PMID 39154024, 2024). "For ovarian and cervical carcinoma, similar studies showed increased expression of MTA1 in aggressive tumors characterised by a high tumor stage." (PMID 36689059, 2023). "Regarding survival, a higher recurrence-free survival time was shown in tumor samples with nuclear expression of MTA1." (PMID 36689059, 2023). "Mechanistically, FTO acts as a tumor suppressor by inhibiting MTA1 expression, recognized by the m6A reader IGF2BP2, in an m6A-dependent manner." (PMID 37580808, 2023). "MTA1 is reported to be overexpressed in a wide range of cancer types and this overexpression correlates with tumor grade, poor prognosis, and invasion status of the tumor." (PMID 37509346, 2023). "Collectively, these experiments indicate that the CXXC5–CRL4B–NuRD (MTA1) complex has a significant effect on promoting tumor growth, and that it does so by repressing target genes, including TSC1." (PMID 36539038, 2023).
tumor (continued). "With higher tumor size, a significant increase in expression of MTA1 in the nucleus as well as the cytoplasm was shown." (PMID 36689059, 2023). "According to the Kaplan–Meier survival curves analysis a significantly higher disease-free survival was shown in tumor samples with nuclear expression of MTA1 (p = 0.004)." (PMID 36689059, 2023). "In more detail, MTA1 remodeled the tumor microenvironment into a CD8+ T cell-enriched and classical macrophage-lacking microenvironment." (PMID 35350571, 2022). "In the coculture system, cancer cells expressing higher MTA1 suppressed the tumor-killing effect of T cells, and additional macrophages increased the killing effects of T cells on cancers." (PMID 35350571, 2022). "MTA1 protein can be expressed in various zones of tibial GP, and the results were consistent with the tumor." (PMID 35872845, 2022). "A previous study demonstrated that HIF1α stabilized by Lysine-specific demethylase 1 cooperates with CBP and MTA1 to enhance VEGF induced tumor angiogenesis." (PMID 35355718, 2022). "According to the qChIP assays, knockdown of either RUNX2 or MTA1 consistently led to a dramatic increase in histone pan-H3 acetylation at the promoters of target tumor suppressor genes." (PMID 35534547, 2022). "Thereby, HDAC1 stimulates oxygenation of the tumor microenvironment by upregulating HIF-1α expression through HDAC1/MTA1." (PMID 35327319, 2022). "The results derived from CCLE database analysis also displayed a significant difference in the expression of CCL2 between tumor cells with high or low MTA1 levels." (PMID 35350571, 2022). "MTA1 expression in tumor tissues from the V+E@Gel group was significantly reduced by 80% in comparison with the saline group." (PMID 36145556, 2022). "We found that the interaction between tumor cells and T cells in the MTA1-overexpressing group was significantly decreased compared to that of the control and MTA1-knockdown groups." (PMID 35350571, 2022). "The importance of MTA1 on macrophages for the antitumor effects of CD8+ T cells implies an immunosuppressive tumor microenvironment by MTA1 overexpression in cancers." (PMID 35350571, 2022). "In this study, the results suggested an MTA1-derived immunosuppressive signature in the tumor microenvironment." (PMID 35350571, 2022). "There are certain limitations to roundly defining the detailed functions of CD8+ T cell subtypes and macrophage subtypes induced by MTA1-high tumor cells." (PMID 35350571, 2022). "We aimed to explore how MTA1-overexpressing tumors affected the function of DCs and macrophages; therefore, we divided the samples into the MTA1-high group and the MTA1-low group based on the MTA1 expression level in tumor cells." (PMID 35350571, 2022). "Subsequent investigation showed that decreased macrophages at high MTA1 levels significantly affected the tumor killing of T cells." (PMID 35350571, 2022). "In this study, we identified a new upstream regulator of MTA1 and validated this new FOXP3-MTA1 regulatory pathway through in vitro and in vivo experiments, identifying a new pathway for the study of tumour metastasis." (PMID 34307133, 2021). "The authors showed that PKD1 phosphorylated MTA1 and triggered polyubiquitination and proteasomal degradation of MTA1, therefore inhibiting tumor cell migration and invasion." (PMID 33807058, 2021). "Our genome-wide analysis indicated that the Snail/PRMT5/NuRD(MTA1) complex play important roles in cell migration and tumor cell invasion." (PMID 33953349, 2021). "M6A enrichment in site 4 region of MTA1 mRNA was also found increased in CRC tumor tissues versus paired adjacent normal tissues." (PMID 34218271, 2021). "In vivo experiments also confirmed that MVD and tumor growth rate decreased after MTA1 silencing in NSCLC, and 70% of the nude mice survived for more than 30 days." (PMID 32410569, 2020).